LEP (leptin)
Diseases named in the same sentence as LEP in open-access papers (continued):
Sharing a sentence is not in itself a finding about the gene and the disease.
Obesity (continued). "In summary, APDs have the potential to influence leptin levels directly or indirectly through the effect of obesity and subsequent leptin resistance." (PMID 35047549, 2021). "Female cynomolgus macaques have been observed to develop spontaneous obesity in adulthood, with bodyweight showing positive correlation with increased serum leptin levels." (PMID 34630614, 2021). "She presented with undetectable leptin, and remarkable clinical history of rapid weight gain leading to obesity after normal birthweight, even after restricted caloric diet." (PMID 34504472, 2021). "Obesity is also associated with an elevated level of pro-inflammatory cytokines and chemokines IL-6, RANTES, and IL-1β and of the hormone leptin, which maintains homeostatic control of AT mass." (PMID 34248964, 2021). "High level of IL-6 is also another key signature of severe SARS-CoV, MERS-CoV, and pandemic H1N1 influenza A viral infections In individuals with obesity, adipocytes secrete pleiotropic leptin and pleiotropic adipocyte-specific IL-6 cytokine." (PMID 34220807, 2021). "Dysregulated (up or down) secretion of several adipose-specific cytokines -so-called adipokines- such as adiponectin, leptin and resistin, is a common feature of dysfunctional adipose tissue in obesity and PCOS." (PMID 34407095, 2021). "In summary, the role of HFD-induced obesity on lung tumorigenesis was elucidated both in vivo and in vitro in this study, and highly expressed leptin mediated the activation of STAT3 pathway was likely involved in the mechanism." (PMID 33708630, 2021). "Despite knowing that leptin is one of the principal suppressors of appetite and leptin’s link with obesity, the treatment of obesity using leptin-based therapeutics remains to be fully explored." (PMID 34084149, 2021). "The altered expression of leptin and its receptor leads to leptin resistance, which plays a critical role in obesity-related complications." (PMID 34084149, 2021). "Leptin resistance is characterized by decreased satiety, excessive food consumption, and an increase in total body mass and a significant issue in obesity." (PMID 34944525, 2021). "Most importantly, adipokine-leptin is closely related not only to obesity but also to the ventilation response." (PMID 32886313, 2021). "Integrative cistromic and transcriptomic analysis showed that REV-ERB-dependent leptin signaling in the arcuate nucleus plays an important role in the control of diurnal leptin sensitivity and food intake in diet-induced obesity." (PMID 34557221, 2021). "Raised plasma levels of leptin in obesity and T2DM reflects leptin resistance, and relatively decrease response to leptin in regulating energy balance and cell metabolism." (PMID 33925808, 2021). "Leptin is the adipocyte-derived ‘anti-obesity’ or ‘starvation response’ hormone (depending which extreme of its circulating concentration range is being focused on)." (PMID 34502119, 2021). "Leptin produced by obesity-altered adipose stem cells (obASCs) is a key factor for mediating tumor metastasis." (PMID 34350120, 2021). "CB1 receptor inactivation improves the response to intracerebroventricular leptin injection, and restores the leptin sensitivity to help to reduce obesity in a DIO mouse model." (PMID 34064024, 2021). "Hyperleptinemia (high levels of adipocytokine leptin) is an important manifestation of obese state and has been shown to mediate myriad biological impacts of obesity including carcinogenesis." (PMID 34389732, 2021). "In obesity-related kidney disease, several adipokines have been implied such as leptin, adiponectin, tumor necrosis factor α (TNF-α) or interleukin 6 (IL-6)." (PMID 33928108, 2021). "In obesity, serum leptin levels are generally elevated because leptin resistance occurs and the feeling of hunger continues despite high energy stores." (PMID 34074279, 2021). "Our data indicate that Zn, Se, and co‐administration attenuated the elevation of leptin following HFD‐induced obesity." (PMID 34631042, 2021).
Obesity (continued). "By these pleiotropic mechanisms obesity impairs immune surveillance and the higher leptin concentrations produced by adipose tissue and that characterize obesity substantially contribute to such immune response dysregulation." (PMID 33804765, 2021). "The leptin/BMI ratio increased with the degree of obesity, the presence of metabolic syndrome, or diabetes." (PMID 34829886, 2021). "In this study, we investigated the effect of leptin administration to pregnant miceon the development of diet-induced obesity, food choice, and gene expression in the liver and muscles of theoffspring with regard to sex." (PMID 34782887, 2021). "Ablation of autophagy-related protein 7 (Atg7) in the hypothalamus shows increased food intake and body weight, obesity and leptin resistance." (PMID 33849593, 2021). "All of them had early onset of extreme obesity, seven had hyperphagia, three had altered growth and elevated leptin levels, two had hypogonadotropic hypogonadism, dyslipidemia, and hyperinsulinemia." (PMID 34390703, 2021). "Mice lacking Stat3 in Lepr-expressing neurons develop hyperphagic obesity supporting the important role of Stat3 signaling in mediating central leptin effects." (PMID 34390703, 2021). "In the case of obesity, a decrease in plasma leptin levels can restore hypothalamic leptin sensitivity and effectively reduce weight gain." (PMID 34646336, 2021). "Obesity and overweight are frequent in SMI and are associated with increased leptin levels, closely correlated with BMI and AP treatment, as confirmed in the present study and shown previously in numerous other studies." (PMID 34122163, 2021). "Leptin synthesis is proportional to adipose size; thus, in obesity, the production of leptin is increased in PVAT and visceral adipose tissue." (PMID 34836100, 2021). "We reviewed the literature on the relationship between diet and leptin, which suggests that addressing leptin resistance through dietary interventions can contribute counteracting obesity." (PMID 34899599, 2021). "In patients with leptin deficiency, recombinant leptin replacement therapy suppresses appetite and increases energy expenditure and leptin has been developed as a treatment for obesity." (PMID 33796069, 2021). "Perhaps unsurprisingly, the discovery of leptin and its unequivocal importance for obesity, a global health threat, led to a strong focus on the weight-regulating and potential anorexic effect of leptin." (PMID 34066779, 2021). "Celastrol's ability to significantly decrease PERK phosphorylation, as seen in the study of leptin and obesity, therefore provides a direct link between Celastrol, decreased ER stress and increased leptin sensitisation." (PMID 34490381, 2021). "To date, although much research work has been conducted in diet-induced obesity (DIO) micewith leptin resistance, the molecular mechanisms largely remains elusive." (PMID 33849593, 2021). "Numerous data support the concept that leptin represents an important regulator of regional sympathetic nerve activity with pathophysiological implications in obesity." (PMID 34068919, 2021). "Subjects with obesity had higher fasting plasma insulin concentrations, indicating insulin resistance, and higher fasting leptin concentrations." (PMID 34331964, 2021). "Since its discovery, leptin has been considered an attractive therapeutic target for the treatment of obesity and type 2 diabetes, due to its potency for the endocrine control of energy balance." (PMID 33935782, 2021). "In a virus CDV infection-induced obesity model in mice using intracerebral infection, hyperinsulinemia and alteration in leptin signaling were observed." (PMID 34795562, 2021). "In particular, hypothalamic inflammation observed in chronic inflammatory conditions such as obesity or upon fat rich diet is considered crucial in leptin resistance development." (PMID 33804765, 2021).
Obesity (continued). "We reviewed all publication from PubMed database using the terms ((“breast neoplasms”[MeSH Terms] AND (“leptin”[MeSH Terms] AND (“obesity”[MeSH Terms] OR (“metabolic syndrome”[MeSH Terms] AND (“micrornas”[MeSH Terms]." (PMID 33482868, 2021). "NPY is elevated in obesity and promotes energy storage, and decreases in response to administration of leptin or insulin." (PMID 33716966, 2021). "The Adiponectin (ADIPOQ) epigenetic status also has relationship with obesity, and association has been reported between LDL-cholesterol levels and DNA methylation of both LEP and ADIPOQ." (PMID 34552557, 2021). "Protection from diet-induced obesity (most evident in males) and leptin resistance; delayed the onset of diet-induced infertility in females." (PMID 34502119, 2021). "The typical modern diet-induced obesity is characterized by hyperleptinemia (elevated levels of leptin) and resistance to the body weight reducing effects of leptin." (PMID 33995281, 2021). "Both had early-onset severe obesity, remarkable hyperphagia, hyperinsulinism, and low leptin serum levels." (PMID 34504472, 2021). "Leptin, an obesity-related peptide, has also been reported to increases the deposition of β-amyloid." (PMID 34326804, 2021). "Accumulating evidence suggests that leptin is involved in regulating tumor cell proliferation, invasion, and migration and is considered an intermediate for obesity-related cancers such as breast cancer and colon cancer." (PMID 33708630, 2021). "As such, increased leptin to adiponectin ratio (LAR) has been reported to be a good marker for assessing obesity-induced low-grade inflammation than isolated leptin or isolated adiponectin concentrations and has been shown to be strongly associated with MetS." (PMID 34844584, 2021). "Several evidences of dysfunction in leptin signaling have been identified in diabetes, obesity, and metabolic disorders." (PMID 34912298, 2021). "Obesity, particularly in the context of type 2 diabetes (T2D), is related to the development of resistance to the effects of leptin." (PMID 34360982, 2021). "Since this is the result of reduced sensitivity to leptin signaling, leptin resistance is involved in obesity." (PMID 32886313, 2021). "High levels of leptin increase oxidative stress in endothelial cells, reduce vasodilatation, and contribute to obesity-related hypertension." (PMID 34422210, 2021). "Leptin is a hormone secreted by adipocytes, and it is known as the paracrine factor released upon obesity and metabolic syndrome 27,28." (PMID 33967621, 2021). "At the same time, new evidence shows blood–brain-barrier (BBB) changes in obesity (probably similar to BBB alterations in MS), promoting the idea that leptin resistance is caused by the affected transport of leptin at BBB level." (PMID 34207197, 2021). "Elevated leptin levels are associated with insulin resistance and with development of T2DM, obesity, and hypertension." (PMID 33668426, 2021). "With the exception of adiponectin, the other three adipokines, i.e., leptin, visfatin, and resistin, are proinflammatory and their levels increase during obesity." (PMID 34737743, 2021). "It was found that resveratrol attenuates the expression of leptin in adipocytes, elevates phosphorylation of STAT3 in the hypothalamus, and restores leptin resistance in adult offspring from HF rat mothers attenuating obesity." (PMID 34084149, 2021). "Yet, in diet-induced obesity leptin cellular signaling appears to be intact, suggesting that the higher leptin levels are not a result of resistance, but rather some individuals need higher levels in order to engage the neuronal circuits." (PMID 34680059, 2021). "Studies with administration of recombinant leptin in mice began in 1995 and showed that its use ameliorated their obesity through reduction of food intake and higher energy expenditure." (PMID 34504472, 2021). "Among adipokines, leptin positively correlated with age, CV history, obesity, disease activity, CRP, IMT, and PWV." (PMID 34680168, 2021).
Obesity (continued). "The proteins with the largest effect estimates were leptin and IGFBP2, both of which have been previously reported to be associated with obesity, T2D and MetS." (PMID 34016094, 2021). "A single injection of leptin onday 12 of pregnancy prevented hyperglycemia in the offspringwith obesity and tended to decrease the rate of diet-inducedobesity development in the male offspring." (PMID 34782887, 2021). "We demonstrate that patients with IIH have dysregulated systemic metabolism, in excess of that mediated by obesity, being more insulin resistant in the context of hyperleptinemia and adipocyte leptin hypersecretion." (PMID 33848268, 2021). "Although the coexistence of elevated leptin levels with obesity is widely interpreted as evidence of “leptin resistance”, the relationship between leptin and anorexia nervosa/bulimia has not been completely elucidated." (PMID 34769125, 2021). "Changes in glucose metabolism due to the application of a high-fat diet for 24 hours explain the reduced level of leptin in human circulation and thus contribute to a high-fat diet in promoting weight gain and obesity." (PMID 34084149, 2021). "Obesity-induced changes in adipokine secretion can modify the adipose tissue-liver crosstalk and the ratio between leptin and adiponectin has been proposed as a superior biomarker of NAFLD than adiponectin or leptin measurements alone." (PMID 34638880, 2021). "As adiponectin is mainly produced and secreted by white adipocytes, these data suggest that IL-6 signaling in adipocytes contributes to reduced circulating adiponectin leptin levels in people with obesity." (PMID 33572989, 2021). "In this respect, fragments of the whole leptin molecule have already been identified as having anti-obesity actions in various studies." (PMID 33440796, 2021). "It has been shown that the level of the free form of leptin in obesity increases due to small sOB-R concentrations." (PMID 34407095, 2021). "Hyperphagia and weight gain are typical characteristics of leptin deficiency; however, leptin levels are seen to be increased in some cases of obesity and diabetes owing to leptin resistance." (PMID 34912298, 2021). "Both obesity and chronic hyperleptinemia are necessary to cause LR in DIO models, thereby suggesting that leptin sensitivity restoration must be achieved by addressing both of these conditions." (PMID 34899599, 2021). "In vivo experiments on murine models revealed that myeloid proliferation is enhanced by high leptin concentration in obesity." (PMID 33803348, 2021). "A link between autoimmunity and obesity has been noted, with leptin as a factor linking the two conditions." (PMID 33746952, 2021). "In contrast to adiponectin, increased leptin levels usually occur in obesity, and here leptin resistance is also assumed." (PMID 34780545, 2021). "In the present study we provide new insights on the mechanisms by which chronic central leptin administration exert its anti-obesity actions through the CNS." (PMID 33924880, 2021). "In summary, our work evidences the major role of leptin signaling on NLRP3 inflammasome activation in the ovary of mice during early obesity." (PMID 34805147, 2021). "Low adiponectin, high leptin, and TNF-α levels were associated with obesity, NASH, and play an important role in CRC-hepatic metastasis." (PMID 34722019, 2021). "Others also found that elevated leptin levels correlated with more severe RA, as well as obesity and CVD in RA." (PMID 34680168, 2021). "DPP4 plasma levels are related to several markers of obesity, such as BMI, waist circumference, plasma triglyceride levels, leptin concentration, and fat cell volume." (PMID 34178021, 2021). "First, we focused on the association between targets of compounds in AMGB and adipocytokine signaling pathway since the adipocytokine signaling pathway including leptin is considered the main pathophysiology of obesity at the molecular level." (PMID 34944525, 2021).
Obesity (continued). "In 12- to 16-year-olds, higher NEFA levels were observed in females with obesity independently of leptin levels." (PMID 35071145, 2021). "High leptin levels predict the occurrence of major adverse cardiac events in patients with established CAD, independently of obesity and other cardiovascular risk factors." (PMID 34679472, 2021). "In this study, we evaluated the antihypertensive, antihyperlipidemic, biomarkers of obesity (leptin and adiponectin), and diuretic effects of the hydroethanolic extract of A. officinarum in obesogenic feed-induced hypertensive rats." (PMID 34305591, 2021). "Several in vivo and in vitro studies have shown that they have anti-obesity effects by modulating lipolysis and lipogenesis, stimulating browning, and varying leptin levels." (PMID 34769261, 2021). "Taking all these results together, we suggest the name of “leptin paradox” to explain the dual role of leptin in cancer, in a similar way to obesity." (PMID 34202969, 2021). "The overall values of age, BMI, and high leptin were similar to other studies about the obesity population, and these facts proved the need for other classification systems." (PMID 34055005, 2021). "On the other hand, in 12- to 16-year-olds, the significantly higher insulin levels observed in males and females with obesity remain significantly higher after adjusting by leptin." (PMID 35071145, 2021). "In a mouse model study, obesity mediated thyroid carcinogenesis by increasing insulin resistance, oxidative stress, leptin, and cytokines related to inflammation." (PMID 33846511, 2021). "In the quest for effective control of obesity, four hormones were discovered to havea link; insulin, leptin, ghrelin and obestatin and the growth hormone secretagoguereceptor (GHS-R)." (PMID 34879109, 2021). "In general, a diet-induced maternal obesity induced obesity, altered brain appetite, insulin and leptin resistance, hypertensive disorders, reduced pancreatic beta-cell function, hepatic steatosis, and nonalcoholic fatty liver disease in the offspring." (PMID 33572203, 2021). "Leptin and insulin are equally important in the metabolic features of the pathophysiology of obesity, and PREP1 plays a primary role in organogenesis and metabolism." (PMID 34327205, 2021). "It is documented that adipocytes express and secrete an array of adipokines including leptin and resistin, which are involved in the pathogenesis of obesity and type 2 diabetes." (PMID 34063048, 2021). "The maternal metabolic status can affect DNA methylation of LEP profile at birth, affecting metabolic remodeling of obesity." (PMID 34552557, 2021). "Initially, in diet-induced obesity in animal models, the impairment in leptin-induced NO synthesis and release was compensated by enhanced EDHF-mediated vasodilation." (PMID 34836100, 2021). "Obesity proceeds from a chronic energy imbalance and is characterized by persistent hyperleptinemia and central leptin resistance." (PMID 33920604, 2021). "Leptin resistance has been demonstrated in both murine models and human obesity, with reduced transport across the blood-brain-barrier (BB)." (PMID 33717095, 2021). "TNF-α for example, which is increased in patients with obesity, has the potential to inhibit adiponectin production in human adipocytes in vitro while leptin production remained intact." (PMID 33557015, 2021). "Leptin is a pro-inflammatory adipokine that controls body weight and appetite, and it is a major determinant of obesity." (PMID 34680168, 2021). "On the other hand, IUGR is characterized by a transient prenatal downregulation of insulin- and leptin signaling, followed by a postnatal upregulation during catch-up growth resulting in the same pathology as obesity." (PMID 34211985, 2021). "Obesity mediated carcinogenesis occurs via imbalance of adipocytokines that includes enhanced production of leptin (oncogenic adipokine) with lessened release of adiponectin." (PMID 34535145, 2021).